CXCR3 (C-X-C motif chemokine receptor 3)
Diseases named in the same sentence as CXCR3 in open-access papers (continued):
Sharing a sentence is not in itself a finding about the gene and the disease.
acute myeloid leukemia (7 papers, 2015 to 2024). Acute myeloid leukemia (AML) is a group of neoplasms arising from precursor cells committed to the myeloid cell-line differentiation. "The mentioned changes may explain the drop in PD-L1 expression in the fibrotic phase of MPN because The Cancer Genome Atlas (TCGA) data documents a strong positive association between M-CSF, CXCR3 expression, and PD-L1 expression in another myeloid malignancy-acute myeloid leukemia." (PMID 36266510, 2022). "Statistical assessment of patients with acute myeloid leukemia (AML) and myelodysplastic syndromes (MDS) treated with ICIs revealed enrichment of IFNγ+ IL-17- CD8+ T and CXCR3+ CCR6+ Th17/Th1 cells in BALF in the group developing pneumonia." (PMID 38426102, 2024). "Our analysis data suggested the predictive potential of CXCR as four CXCR members (CXCR3, CXCR4, CXCR5, and CXCR6) were significantly related to better clinical outcomes in HNSCC, as reported in acute myeloid leukemia." (PMID 35978426, 2022). "Thus, we have examined the serum levels of these chemokines in parallel with their related cognate receptors (CXCR1, CXCR3 and CXCR4) in AML (acute myeloid leukemia) patients prior and post BMT (bone marrow transplantation) therapy." (PMID 34711015, 2021).
basal cell carcinoma (7 papers, 2014 to 2022). A carcinoma involving the basal cells. "Keratinocytes derived from basal cell carcinoma express CXCR3 and proliferate in response to signalling through this pathway." (PMID 35844527, 2022). "In addition, CXCL11 is capable of promoting immunosuppressive indoleamine 2,3-dioxygenase (IDO) expression in human basal cell carcinoma and enhancing keratinocyte proliferation, thus potentially reducing the anti-tumor activity of any infiltrating CXCR3+ effector T cells." (PMID 30320116, 2018). "Less well understood is the role of CXCR3 and its ligands in non-melanoma skin cancers such as squamous cell carcinoma (SCC) and basal cell carcinoma (BCC)." (PMID 30320116, 2018).
chronic obstructive pulmonary disease (7 papers, 2004 to 2025). A chronic and progressive lung disorder characterized by the loss of elasticity of the bronchial tree and the air sacs, destruction of the air sacs wall, thickening of the bronchial wall, and mucous accumulation in the bronchial tree. "CXCR3-dependent accumulation and activation of monocytes or macrophages have been shown to play a critical role in homeostatic arterial remodeling in response to hemodynamic stresses in chronic obstructive pulmonary disease, as well as in mycobacterial infection." (PMID 34527676, 2021). "Upregulation of CXCL10, the ligand of the chemokine receptor CXCR3 found on macrophages, has been observed in the bronchiolar epithelium of patients with Chronic Obstructive Pulmonary Disease (COPD) compared to non-smokers or smokers with normal lung function." (PMID 31681519, 2019).
Cognitive impairment (7 papers, 2022 to 2025). Abnormal cognition is characterized by deficits in thinking, reasoning, or remembering. "It has been reported that the primary function of microglia CXCR3 is microglia recruitment to CXCR3 ligands, leading to dendrite loss and cognitive deficits after brain injuries." (PMID 37438982, 2023). "Tissue specific activation of the interferon alpha and beta receptor subunit 1 (IFNAR1) and the C-X-C Motif Chemokine Ligand 10 - C-X-C Motif Chemokine Receptor 3 (CXLC10-CXCR3) axis in murine brain endothelial and epithelial cells may manifest as cognitive impairment." (PMID 38562226, 2024). "As the AAB targets F2R/PAR-1, CXCR3, and STAB1 are involved in inflammatory processes this finding points to a distinct inflammatory mechanism in cognitive impairment in PCS/ME/CFS in contrast to vasoconstriction in the previous cohort of non-COVID ME/CFS." (PMID 36238301, 2022). "The study examined the interaction between five hub genes (Cxcl10, Gbp2, Cxcl12, Cxcr3, Ifih1) and four distinct immune cell types (M1 macrophages, NK resting cells, memory CD4 T cells, naive CD8 T cells) in mice brain tissues affected by cognitive impairment." (PMID 39286150, 2024). "CXCR3 blockers have reached clinical trials for peripheral inflammatory conditions but have not yet been tested in patients with dementia or other cognitive disorders." (PMID 37075107, 2023).
Crohn disease (7 papers, 2005 to 2024). A gastrointestinal disorder characterized by chronic inflammation involving all layers of the intestinal wall, noncaseating granulomas affecting the intestinal wall and regional lymph nodes, and transmural fibrosis. "Also, reduced mRNA levels of canonical CXCR3A, but increased mRNA levels of CXCR3-alt, were found in CD3 positive lymphocytes in peripheral blood from patients with Crohn’s disease." (PMID 29379506, 2017).
hepatitis C (7 papers, 2012 to 2025). "In hepatitis C, the chemokine receptor CXCR3 and its ligands have been shown to be associated with stage of fibrosis suggesting a role of these chemokines in HCV associated liver damage by yet incompletely understood mechanisms." (PMID 22792160, 2012). "In hepatitis C virus infection, IP-10 was reported to recruit inflammatory CXCR3+ T lymphocytes to enhance the inflammatory response." (PMID 37701855, 2023). "Increased CXCL10 and CXCR3 gene expression in chronic hepatitis B and hepatitis C patients were reported to correlate with the severity of the disease." (PMID 35307625, 2022). "The number of macrophages identified by CXCR3 immunostaining in recurrent hepatitis C ranged from 0 to 30; the mean ± SD was 6.2 ± 8.5 and the median was 1.0." (PMID 29854831, 2018). "CXCL10 is well known in hepatitis C as a hepatocyte-derived chemotactic ligand and initiator of inflammatory cascades via its cognate receptor C-X-C motif receptor 3 (CXCR3)." (PMID 29854831, 2018). "Macrophage infiltrating liver tissue post LT can distinguish between ACR by upregulation of CXCR3 and recurrent hepatitis C by predominant CD11b." (PMID 29854831, 2018). "Indeed, our data indicate that hepatitis C may be associated with impaired activity of peripheral CXCR3(+) NK cells because we found that in HCV infected patients_specifically the CD56BrightCXCR3(+) subset displayed decreased degranulation and IFN-γ secretion in response to human HSC." (PMID 22792160, 2012). "In hepatitis C the CXC-chemokine receptor CXCR3 and its ligands (CXCL9, CXCL10, CXCL11) have gained specific attention because various studies demonstrated elevated levels of CXCR3 ligand CXCL10 to be predictive of the failure to response to HCV therapy and to be associated with stage of fibrosis." (PMID 22792160, 2012). "CD11b expression highlighting macrophages of BDM origin was in favor of recurrent hepatitis C (P < 0.001) than in ACR (P = 0.44), while CXCR3 expression by hepatocytes was in favor of ACR (P = 0.001)." (PMID 29854831, 2018).
myocardial infarction (7 papers, 2015 to 2025). Gross necrosis of the myocardium, as a result of interruption of the blood supply to the area, as in coronary thrombosis. "In cardiac transplantation, increased expression of CXCR3 ligands is linked to transplant rejection, while in myocardial infarction, the recruitment of CXCR3-positive cells is critical for cardiac repair." (PMID 40786052, 2025). "During myocardial infarction, the dual role of CXCR3 in inflammatory processes might enable CXCR3+ cells to set off an appropriately rapid and robust inflammatory response in the beginning." (PMID 30210493, 2018). "In contrast, Cxcl10–/– mice subjected to myocardial infarction were characterized by enhanced adverse ventricular remodeling, early expansion of the fibrotic scar, and increased neutrophil infiltration with marked reduction of recruitment of CXCR3 expressing leukocytes and T cells." (PMID 30210493, 2018). "Our suggestion that CCR4 and CXCR3 might participate in neuroinflammation is based on previous reports associating CCR4 with recruitment of white blood cells and production of cytokines after myocardial infarction and correlated CXCR3 with leukocyte accumulation in focal stroke and gliosis." (PMID 27635404, 2016).
pneumonia (7 papers, 2018 to 2026). An acute, acute and chronic, or chronic inflammation focally or diffusely affecting the lung parenchyma, caused by an infection in one or both of the lungs (by bacteria, viruses, fungi, or mycoplasma.). "Differential expression of IL-17 in BAL IFNγ+ IL-17- CD8+ T and CXCR3+ CCR6+ Th17/Th1 cells was noted in BAL fluid of patients with ICI-Pneumonitis compared to patients with pneumonia; however, larger studies are needed to confirm these findings." (PMID 34675810, 2021). "The results of CXCR3 immunostaining showed rare CXCR3 expressing cells, both in pneumonia and in controls." (PMID 30026741, 2018). "At the site of the pathologic response to the disease, relative expression of CXCR3 was higher compared to patients with pneumonia of different etiology." (PMID 30026741, 2018). "Moreover, patients with active TB showed a significantly lower expression of CXCR3 in the lung compared to patients with pneumonia in both CD4+ and CD8+ cell subsets." (PMID 30026741, 2018). "The results showed that in TB patients, CXCR3 expression in CD4+ and CD8+ cell subsets was lower in the lung compared to the periphery, whereas in pneumonia, the CXCR3 expression in CD4+ and CD8+ cell subsets was lower in the periphery compared to the lung." (PMID 30026741, 2018). "Moreover, the expression of CXCR3 and CD26 was evaluated in BALCs and PBMCs by flow cytometry in six patients with active TB and eight patients with pneumonia." (PMID 30026741, 2018).
renal carcinoma (7 papers, 2015 to 2022). A carcinoma arising from the epithelium of the renal parenchyma or the renal pelvis. "Also, TNF-α could strongly up-regulate CXCR3 to facilitate invasion and metastasis of renal carcinoma, and high expression of CXCR3 was associated with poor prognosis." (PMID 33324682, 2020). "Recent data has shown that TNF-α significantly increased the expression of CXCR2 and CXCR3 and their related ligands in renal cancer cells enhancing the migration, invasion and EMT." (PMID 29416784, 2018).
respiratory infections (7 papers, 2018 to 2024). "In humans, little is known about CXCL10/CXCR3 in the context of respiratory infections." (PMID 31815739, 2020). "The loss of CXCR3+CCR5+CCR6−CXCR6− MAIT cells (which predominated in healthy individuals) may be particularly detrimental to respiratory infections such as Mtb, as multiple studies have demonstrated a role for CCR5 and CXCR3 co-expression in trafficking of T cells to the lung during TB infection." (PMID 29868028, 2018).
ulcerative colitis (7 papers, 2014 to 2025). An inflammatory bowel disease involving the mucosal surface of the large intestine and rectum. "Our previous studies have shown that QCWZD had a prominent therapeutic effect on DSS-induced UC in rats, and we have made a preliminary study on the mechanism of QCWZD in treating ulcerative colitis from IP10/CXCR3 axis–mediated inflammatory response." (PMID 29234405, 2017). "Our previous study found that Qingchang Wenzhong Decoction (QCWZD) can significantly improve the clinical symptoms of UC and ameliorate dextran sulphate sodium- (DSS-) induced ulcerative colitis in rats by downregulating the IP10/CXCR3 axis–mediated inflammatory response." (PMID 29234405, 2017). "Contrary to the destructive mechanism of IP10/CXCR3 axis, the MSP/RON signalling pathway plays a protective role in the pathogenesis of ulcerative colitis." (PMID 29234405, 2017). "The expression of the three ligands of CXCR3 (CXCL9, CXCL10, and CXCL11) is significantly increased in various diseases such as interstitial cystitis, ulcerative colitis, and myositis, and previous studies found that blocking CXCL10 can reduce the degree of the damage of these diseases." (PMID 35036436, 2022).
acute respiratory distress syndrome (6 papers, 2016 to 2025). Progressive and life-threatening pulmonary distress in the absence of an underlying pulmonary condition, usually following major trauma or surgery. "Both CXCL10 and its cognate receptor CXCR3 are expressed by activated neutrophils and are responsible for their recruitment to the lungs in acute respiratory distress syndrome models." (PMID 28852269, 2017). "For example, CXCR3, the receptor for CXCL10 and CXCL11, is commonly associated with expression on T cells and lymphocytes but has been shown to be expressed on lung neutrophils from patients with acute respiratory distress syndrome." (PMID 37809107, 2023). "CXCR3 was highly expressed in inflamed neutrophils in BAL obtained from influenza virus-infected mice, and a reduction of neutrophils in BAL was reported in CXCR3 or IP-10 knockout mice with viral- or acid-induced acute respiratory distress syndrome." (PMID 27965774, 2016).
Allergy (6 papers, 2010 to 2024). An allergy is an immune response or reaction to substances that are usually not harmful. "The downregulation of CXCR3 and CXCR6 gene expression in circulating mononuclear cells may be a marker of type 2, IgE-predominant responses associated with environmentally driven allergic disease." (PMID 33804792, 2021). "Previously, in allergic reactions, increased mRNA expression of different proteins, namely, the chemokine interferon-γ-inducible protein-10 (CXCL10) and the related CXC chemokine receptor 3-activating chemokines (CXCR3) macrophage migration inhibitory factor (MIF) and IP-9, was identified." (PMID 39062959, 2024).
brain tumor (6 papers, 2007 to 2021). "CXCL10 and CXCR3 stimulate DNA synthesis and cell proliferation in vitro, suggesting that this chemokine could play an important role in brain tumor biology." (PMID 26506595, 2016). "In addition, LRP1regulates CXCR3 to suppress the invasion of primary brain tumors." (PMID 33901269, 2021). "When we evaluated the percentages of IFN-γ-, TNF-α-, and IL-2-producing CD4+ and CD8+ T cells within GBM tumours, we noticed that CXCR3 blockade in the EMP3_KO group reduced CD8+ and CD4+ T cell infiltration into the brain tumour, blood, and spleen." (PMID 33964937, 2021).
chronic hepatitis C (6 papers, 2012 to 2024). "Chronic hepatitis C was associated with a significantly increased frequency of CXCR3(+)CD56Bright NK cells which showed impaired degranulation and impaired IFN-γ secretion in response to HSC." (PMID 22792160, 2012). "Accordingly, we found chronic hepatitis C to be associated with a significantly increased frequency of circulating CXCR3-expressing CD56Bright NK cells." (PMID 22792160, 2012). "Various organ/tissue-specific diseases caused by increased inflammation, such as chronic hepatitis C virus infection, biliary cirrhosis, psoriatic and osteoarthritis, attract NK cells via the CXCR3/CXCL10 axis; meanwhile, CXCL11-targeted CXCR3 promotes antitumor responses." (PMID 31647037, 2019). "However, chronic hepatitis C was associated with a significantly increased percentage of peripheral CXCR3(+)CD56Bright NK cells as compared to HCV(−) controls." (PMID 22792160, 2012). "Here, we compared phenotype and functional activity against primary human hepatic stellate cells of CXCR3(+) NK cell subsets in healthy individuals and chronic hepatitis C." (PMID 22792160, 2012). "Chronic hepatitis C caused by the hepatitis C virus and intrahepatic interferon-gamma (IFN-γ), which causes increases in CXCL10 production by the sinusoidal endothelium and hepatocytes, subsequently attracting T-cells expressing CXCR3 to the liver." (PMID 38816794, 2024). "Reports showing the increased expression of CXCR3+ on CD27+ B cells in chronic hepatitis C support a model where these B cells could bind HCV and trans-infect permissive hepatocytes in the liver." (PMID 34975862, 2021). "Here, we analyzed phenotype and function of CXCR3 expressing NK cells in chronic hepatitis C." (PMID 22792160, 2012). "Moreover, these CXCR3-associated chemokines are associated with intrahepatic inflammation and fibrosis in chronic hepatitis C virus (HCV) infection, and CXCL10 can predict fibrosis progression after liver transplantation for chronic hepatitis C." (PMID 24976843, 2014).
emphysema (6 papers, 2004 to 2025). "CD8+ T cells contribute to emphysema development by releasing perforin and granzymes that injury alveolar septal cells, and ligands for C-X-C chemokine receptor-3 (CXCR3) which bind to this receptor on macrophages to promote macrophage activation." (PMID 32677970, 2020). "In COPD patients, T cells in the peripheral airways exhibit an enhanced ability to express CXCR3 and IFN-γ, and increased IL-17A secretion from Th17 cells, along with its signature protein RORγt, is directly correlated with the severity of emphysema." (PMID 40034710, 2025). "The degree of emphysema, concentration of IL-4, IFN-γ and CXCL10, and expression of CXCR3 and CXCL10 in mice administrated with low dose vitamin D3 were similar to the normally treated mice." (PMID 31737787, 2019). "A pulmonary airway model was designed, and morphological assessment of emphysema, IL-4, IFN-γ and CXCL10 concentration in bronchoalveolar lavage fluids, expression of CXCR3 and CXCL10 were detected." (PMID 31737787, 2019). "We extend these findings by showing CXCR3 expression on lung macrophages and CD4+ T cells in emphysema patients and the functional interplay between Th1-related chemokines and elastolytic MMPs." (PMID 15526056, 2004). "Moreover, cells positive for the CXCL10 receptor CXCR3 and CD8, most likely CD8+ T-cells, are increased in COPD patients and CD8+ T-cells were shown to be involved in the development of CS-induced emphysema." (PMID 38348034, 2024). "The loss of lung function in patients with COPD and emphysema is associated with a high percentage of CD4+ and CD8+ T lymphocytes that express receptors CCR5 and CXCR3, but not CCR3 or CCR4 (both markers of T helper one cells)." (PMID 33953665, 2021). "We found that over 40% of CD14+ cells from participants with emphysema but not control participants were also positive for CXCR3." (PMID 15526056, 2004). "Although human lung macrophages are not known to express CXCR3, we suspected based on the immunohistochemical localization of this chemokine receptor that CD14+ cells in the lungs of ex-smoker individuals with emphysema accounted for much of the total lung CXCR3+ immunoreactivity (data not shown)." (PMID 15526056, 2004). "Interestingly, we could not detect appreciable amounts of I-TAC, another known ligand for CXCR3, in lung lymphocytes of control participants or those with emphysema (data not shown)." (PMID 15526056, 2004).
heart failure (6 papers, 2021 to 2025). Inability of the heart to pump blood at an adequate rate to meet tissue metabolic requirements. "Taken together, these findings suggest that ischemic heart disease drives a broad depletion of CD4+ cells, weakening the adaptive immune repertoire, while end-stage heart failure is associated with preserved CD4+ numbers but selective enrichment of CCR5+CXCR3+ inflammatory subsets." (PMID 41155153, 2025). "Notably, targeting of the CXCL10/CXCR3 axis in addition to cardiac inflammation may constitute a new pharmacological approach for either heart failure or CAD therapy supplementary to present drugs that typically target the sympathetic or renin-angiotensin system or platelets." (PMID 34835155, 2021). "Further analysis of functional subsets revealed a marked reduction in CCR5+ CXCR3+ Trm cells in both CABG patients and recipients compared to donors, indicating a potential impairment in the homing/immigration capacity of Trm cells in pathological conditions (CABG and heart failure)." (PMID 41155153, 2025).